LINC02967 (long independently transcribed non-coding RNA 2967)
Synonyms: AL035661.1
Gene: Long non-coding RNA gene on chromosome 20 (24,930,619 to 24,933,194, forward strand). Ensembl gene ENSG00000274173.
Diseases named in the same sentence as LINC02967 in open-access papers:
LINC02967 is named in the same sentence as 2 diseases in open-access papers, as found by Europe PMC text mining. Sharing a sentence is not in itself a finding about the gene and the disease.
LINC02967 shares sentences with these, for which no sentence is quoted: lobular carcinoma (1 paper); renal cell carcinoma (1).